YTHDC2 (YTH N6-methyladenosine RNA binding protein C2)
Diseases named in the same sentence as YTHDC2 in open-access papers (continued):
Sharing a sentence is not in itself a finding about the gene and the disease.
Autoimmunity (1 paper, 2022). The occurrence of an immune reaction against the organism's own cells or tissues. "m6A elements (FTO, YTHDF2, YTHDF3, or YTHDC2) might target ISG15, stimulate the expression of ISG15, and activate the type I IFN signaling pathway, playing an active role in initiating the autoimmunity in pSS." (PMID 36465909, 2022).
B-cell neoplasm (1 paper, 2021). A group of heterogeneous lymphoid tumors generally expressing one or more B-cell antigens or representing malignant transformations of B-lymphocytes. "Besides, patients with ACC had the higher alteration frequency (2.2%) of amplification than all the other tumours, and all mature B‐cell neoplasms cases with genetic alteration had deep deletion (2.08%) of YTHDC2." (PMID 34312987, 2021).
basal cell carcinoma (1 paper, 2023). A carcinoma involving the basal cells. "Through OCLR algorithm, it can be seen that mRNAsi, EREG-MRNASI value has significant difference between the two clusters (p < 0.05), suggesting that FMR1, LRPPRC, RBMX, YTHDC2 and IGF2BP1 may affect CRC by regulating the pathway of basal cell carcinoma." (PMID 37194014, 2023).
benign prostatic hyperplasia (1 paper, 2024). A non-cancerous nodular enlargement of the prostate gland. "Notably, a high expression of YTHDC2 is observed in PCa as compared to BPH (Benign prostatic hyperplasia) and normal prostate tissues." (PMID 39268470, 2024).
bladder tumor (1 paper, 2025). "Analysis of RNA-seq data from TCGA-BLCA, GTEx, and GSE13507 cohorts also revealed significantly lower YTHDC2 expression in bladder tumor tissues compared to normal tissues." (PMID 41145440, 2025).
brain tumour (1 paper, 2023). "Again, there are several conflicting reports of m6A regulator expression levels among the different brain tumour entities and non-tumour brain tissue, including ALKBH5, WTAP, METTL14, and YTHDC2." (PMID 36831575, 2023).
cardiac hypertrophy (1 paper, 2025). "Inhibition of Ythdc2 also partially impeded the enlargement of cardiomyocyte size and the expression of genes associated with cardiac hypertrophy." (PMID 40000392, 2025). "To elucidate the role of Ythdc2 in ferroptosis and cardiac hypertrophy, we conducted a series of loss‐of‐function experiments." (PMID 40000392, 2025). "Collectively, these results provide compelling evidence that Ythdc2 plays a pivotal role in regulating both ferroptosis and cardiac hypertrophy." (PMID 40000392, 2025). "Our GSH assays revealed diminished GSH levels in cardiac hypertrophy, which were further exacerbated by Ythdc2 overexpression and mitigated by Ythdc2 knockdown." (PMID 40000392, 2025). "This study elucidates the role of Zfp36 in cardiac hypertrophy, specifically detailing its modulatory mechanism via the Ythdc2/SLC7A11/GSH ferroptosis pathway." (PMID 40000392, 2025). "This study provides compelling evidence, for the first time, that Zfp36 is integral in suppressing ferroptosis and reducing cardiac hypertrophy through the Ythdc2/SLC7A11/GSH axis in cardiomyocytes (Graphical Abstract)." (PMID 40000392, 2025). "The initial findings indicated that Zfp36 is involved in mitigating ferroptosis during cardiac hypertrophy by targeting Ythdc2." (PMID 40000392, 2025). "Collectively, these findings highlight the role of Zfp36 in modulating cardiac hypertrophy via the Ythdc2/SLC7A11/GSH‐dependent ferroptosis pathway." (PMID 40000392, 2025). "Together, these findings indicate that Zfp36 modulates cardiac hypertrophy and ferroptosis through its interaction with Ythdc2." (PMID 40000392, 2025). "This study examines the regulatory influence of Ythdc2 on SLC7A11 within the context of cardiac hypertrophy." (PMID 40000392, 2025). "Furthermore, Zfp36 overexpression led to an increase in GSH levels; however, this effect was negated by concurrent Ythdc2 overexpression in the context of cardiac hypertrophy." (PMID 40000392, 2025). "Ythdc2 can bind to SLC7A11 mRNA to accelerate its decay, thereby reducing glutathione levels and aggravating ferroptosis‐induced cardiac hypertrophy." (PMID 40000392, 2025). "Ythdc2 subsequently binds to SLC7A11 mRNA, enhancing its decay, which leads to a reduction in glutathione (GSH) levels, thereby exacerbating ferroptosis and cardiac hypertrophy." (PMID 40000392, 2025). "Ythdc2 interacts with SLC7A11 mRNA, facilitating its degradation and resulting in decreased GSH levels, thereby modulating ferroptosis in cardiomyocytes and influencing cardiac hypertrophy." (PMID 40000392, 2025).
endometrial cancer (1 paper, 2021). Primary or metastatic malignant neoplasm involving the endometrium (mucous membrane that lines the endometrial cavity). "In endometrial cancer patients, higher HNRNPC, YTHDC2, WTAP, VIRMA, IGF2BP3, and HNRNPA2B1 expression is closely associated with worse outcomes and advanced stage." (PMID 34616742, 2021). "More recently, the levels of YTHDC2, HNRNPC, and VIRMA were suggested to be negatively correlated, whereas WTAP was positively correlated, with MHC molecules in endometrial cancer." (PMID 34616742, 2021).
Hepatitis (1 paper, 2025). Inflammation of the liver. "In contrast, other m6A regulators, including METTL3, METTL14, WTAP, FTO, ALKBH5, YTHDC1, and YTHDC2, exhibited different protein expression patterns during ConA-induced hepatitis." (PMID 40092485, 2025).
Hypertension (1 paper, 2023). The presence of chronic increased pressure in the systemic arterial system. "Downregulation of genes such as GNB3, SENP2, and YTHDC2 highlights potential links to hypertension, early mortality, and male fertility issues." (PMID 38681774, 2023).
ischemic stroke (1 paper, 2025). A stroke disorder caused by obstruction of blood flow to the brain, due to thrombotic (local blood clot formation) or embolic (due to a blood clot or other material traveling from another site) event. "Although YTHDC2 is essential for general RNA metabolism, its contribution to neuronal viability and pathogenesis of ischaemic stroke remains poorly characterized." (PMID 41154582, 2025). "Collectively, our findings identified a METTL3/AU020206/YTHDC2/SLC7A11 axis that curbs ferroptotic injury after cerebral I/R and highlight epitranscriptomic modulation of lncRNA stability as a promising therapeutic avenue for ischaemic stroke." (PMID 41154582, 2025).
kidney papillary carcinoma (1 paper, 2025). "Finally, in kidney papillary carcinoma (KIRP), the signature included YTHDC2, IGF2BP2, DNMT3B, TRMT6, HNRNPC, and NSUN5." (PMID 40565233, 2025).
oral squamous cell carcinoma (1 paper, 2020). "Furthermore, we performed IHC staining for YTHDC2 and ALKBH5 proteins in 20 pairs of normal and oral squamous cell carcinoma tissues to confirm such findings." (PMID 32547941, 2020).
paraganglioma (1 paper, 2021). A benign or malignant neoplasm arising from paraganglia located along the sympathetic or parasympathetic nerves. "YTHDC2 expression was significantly correlated with molecular subtypes in ACC, BRCA, COAD, HNSC, LGG, pheochromocytoma and paraganglioma (PCPG), PRAD, stomach adenocarcinoma (STAD) and UCEC." (PMID 34312987, 2021).
periodontitis (1 paper, 2021). An acute or chronic inflammatory process that affects the tissues that surround and support the teeth. "The transcriptome relationships were investigated, and we found there are close correlations among writers, readers and erasers; the CBLL1 and YTHDC2 are the most correlated m6A regulators in expression both in all samples and periodontitis samples, indicating that they function together." (PMID 33724691, 2021).
pneumonia (1 paper, 2025). An acute, acute and chronic, or chronic inflammation focally or diffusely affecting the lung parenchyma, caused by an infection in one or both of the lungs (by bacteria, viruses, fungi, or mycoplasma.). "Similarly, our findings demonstrate that circ_0001239 interacts with YTHDC2, thereby disrupting KLF10 mRNA stability and exacerbating pneumonia-associated lung injury." (PMID 41105618, 2025). "To summarize, our study unveils that METTL3 upregulates circ_0001239 expression via m6A modification, increases the binding of circ_0001239 to YTHDC2, and inhibits KLF10 expression, ultimately worsening lung injury in neonatal mice with Spn-induced pneumonia." (PMID 41105618, 2025). "In conclusion, METTL3 aggravates Spn-induced lung injury via m6A-dependent circ_0001239/YTHDC2/KLF10 axis, thereby providing potential therapeutic targets for severe pneumonia." (PMID 41105618, 2025). "Our experiment aligns with this observation, demonstrating that circ_0001239/YTHDC2-mediated KLF10 upregulation alleviates Spn-induced lung injury, whereas KLF10 downregulation diminishes the protective effect of METTL3 knockdown in neonatal mice with Spn-induced pneumonia." (PMID 41105618, 2025).
psoriasis (1 paper, 2024). An autoimmune condition characterized by red, well-delineated plaques with silvery scales that are usually on the extensor surfaces and scalp. "RT-qPCR results in the skin specimen showed that YTHDC2 was highly expressed in the psoriasis and IMQ group compared to the controls, while METTL3 and IGF2BP2 were decreased in the disease group, which was consistent with the results in GSE30999." (PMID 38436011, 2024). "Our experiments verified that the mRNA level of YTHDC2 was elevated in psoriasis patients, and the expression of METTL3 and IGF2BP2 was significantly decreased." (PMID 38436011, 2024).
rectal cancer (1 paper, 2021). A primary or metastatic malignant neoplasm that affects the rectum. "Our analysis revealed that rectal cancer patients with lower expression of YTHDC2 and METTL14 had a remarkable worse overall survival (P < 0.05)." (PMID 34149792, 2021). "In conclusion, our findings demonstrated that the m6A RNA methylation regulators, specifically YTHDC2 and METTL14, were significantly down-regulated and might be potential prognostic biomarkers in rectal cancer." (PMID 34149792, 2021).
rectal tumors (1 paper, 2021). "The significant up-regulation of YTHDF1, YTHDF2, and METTL3, and down-regulation of ALKBH5, YTHDC2, and METTL14 could be observed in the 6 rectal tumors (P < 0.05), indicating that these m6A regulators may be associated with progression of RC." (PMID 34149792, 2021).
renal carcinoma (1 paper, 2021). A carcinoma arising from the epithelium of the renal parenchyma or the renal pelvis. "However, another study of renal cancer confirmed that the mutation frequency of the m6A regulator YTHDC2 was 55.11% and that of METTL3 was 30.11%." (PMID 33926554, 2021).
rheumatoid arthritis (1 paper, 2024). A chronic, systemic autoimmune disorder characterized by inflammation in the synovial membranes and articular surfaces. "YTHDC2 and METTL3 jointly regulate the expression of adhesion molecule with Ig like domain 2 (AMIGO2), regulate the proliferation and invasion ability of rheumatoid arthritis synovial fibroblasts, and thereby affect the disease progression of rheumatoid arthritis." (PMID 38790013, 2024).
Salmonella Infections (1 paper, 2024). Infections with bacteria of the genus SALMONELLA. "The single-gene GSEA results of this study show enrichment of YTHDC2 in the Salmonella infection pathway." (PMID 38714976, 2024).
Stroke (1 paper, 2025). Sudden impairment of blood flow to a part of the brain due to occlusion or rupture of an artery to the brain. "The current study demonstrated that ischemia/reperfusion injury induced the upregulation of YTHDC2, in line with previously observed changes in YTHDF1 and YTHDF2 after stroke." (PMID 41154582, 2025).
synovial sarcoma (1 paper, 2024). "Among them, METTL3, YTHDC1, YTHDC2, RBMX, and ELAVL1 were significantly upregulated in synovial sarcoma tissue." (PMID 38549939, 2024).
tumor (93 papers, 2018 to 2025). "Previous studies showed that the expression of m6A writers (METTL3, RBM15, WTAP), eraser (FTO, ALKBH5) and reader (YTHDF3, YTHDC2) was associated with pathological stage, tumor stage, andprognosis of patients with GC." (PMID 35977935, 2022). "It is worth noting that YTHDC2 had a high diagnostic value for seven types of tumours, including CHOL (AUC = 0.972), LUSC (AUC = 0.906), THCA (AUC = 0.947), OV (AUC = 0.999), SKCM (AUC = 0.908), TGCT (AUC = 0.996) and UCS (AUC = 0.996)." (PMID 34312987, 2021). "In summary, our study contributes to uncovering cancer promoting or suppressing effects of YTHDC2 in various cancer types comprehensively and provides evidence on the role of YTHDC2 in tumour cell immune infiltration, diagnostic value and clinical prognosis." (PMID 34312987, 2021). "Our results demonstrated that YTHDC2 suppression is frequent and is associated with tumor progression in LUAD." (PMID 33232910, 2021). "In both training and validation cohorts, YTHDC2 was associated with tumor stage (P<0.01), while HNRNPC was up expressed in progressed tumor (P<0.05)." (PMID 32398949, 2020). "While METTL14, WTAP, METTL3, ALKBH5, and YTHDC2 had lower expression in high risk group, indicating that they might be tumor suppressor." (PMID 35077391, 2022). "Notably, downregulation of YTHDC2 was associated with larger tumor diameters and a more advanced stage, indicating that YTHDC2 suppression promotes tumor progression in LUAD." (PMID 33232910, 2021). "Moreover, the pathways associated with tumor progression were investigated, which provides a potential molecular basis for YTHDC2 and METTL14 mediated RC development." (PMID 34149792, 2021). "In both training and validation cohorts, YTHDC2 was associated with tumor stage (P<0.01)." (PMID 32398949, 2020). "From the Sankey diagram, it was clear that RBM15, YTHDC1, and YTHDC2 were associated with more lncRNAs ― over 37% (147/397) ― indicating that these methylation-related enzymes have important catalytic and recognition roles in the occurrence of the tumor formation induced by ALV-J infection." (PMID 35529873, 2022). "IHC results confirmed that YTHDC2 protein level was significantly lower in tumor tissues than in normal tissues." (PMID 41145440, 2025). "This shift was characterized by enhanced proliferation, migration, invasion, and self-renewal capabilities of cancer cells, highlighting YTHDC2’s function as a tumor suppressor." (PMID 41145440, 2025). "YTHDC2 functions as a tumor suppressor in endometrial carcinoma, with its silencing promoting endometrial cancer cell proliferation." (PMID 40986143, 2025). "YTHDC2 expression was significantly lower in aggressive tumor subtypes (MIBC, high-grade, recurrent cases, and T3–T4) compared to less advanced disease." (PMID 41145440, 2025). "In footpad xenograft model, nude mice injected with YTHDC2-overexpressed T24 also showed significantly slower tumor growth than control group." (PMID 41145440, 2025). "Prior studies have linked several genes (LGALS8, PTPN12, YTHDC2, APOBEC3G, GPX3, RASA3, and TSPAN4) to immune responses, highlighting the impact of the tumor microenvironment (TME) on DCIS." (PMID 41020869, 2025). "YTHDC2 exerts its anti-tumor effects via the CYLD/NF-κB signaling pathway, a process modulated by m6A modification." (PMID 40986143, 2025). "Taken together, these results highlight YTHDC2’s role as a tumor suppressor by restraining cell stemness and the self-renewal ability." (PMID 41145440, 2025). "We further detected the effect of YTHDC2 on tumor growth using subcutaneous xenograft models in nude mice." (PMID 41145440, 2025). "To compare YTHDC2 mRNA expression levels between normal and tumor tissues, we analyzed RNA-seq data from 56,938 unique samples in the TNMplot database, comprising 15,648 normal, 40,442 tumor, and 848 metastasis samples." (PMID 41145440, 2025).
tumor (continued). "Our analysis revealed a significant difference in YTHDC2 expression between normal and tumor tissues across 18 of 22 tissue types examined, including bladder." (PMID 41145440, 2025). "Wang's research team substantiates that YTHDC2 exerts tumour‐suppressive effects through the m6A modification‐mediated cylindromatosis/NF‐κB signalling pathway." (PMID 39135292, 2024). "determined through IHC analysis that YTHDC2 acts as an anticancer gene, exhibiting high levels of expression in normal tissues and reduced expression in tumour tissues." (PMID 39135292, 2024). "YTHDC2 plays a pivotal role in cancer biology, exerting varied effects on tumor progression depending on its downstream targets." (PMID 38790013, 2024). "Although the role of m6A in regulating tumors is double-sided, there are reports that m6A promotes or suppresses tumors, but YTHDC2, as an effector molecule after m6A, usually plays a role of tumor suppressor." (PMID 39303913, 2024). "While current research suggests YTHDC2 as a potential tumor biomarker aiding in diagnosis, prognostic evaluation, and treatment selection, further studies are essential to elucidate its mechanisms and clinical applications fully." (PMID 38790013, 2024). "In NSCLC, low YTHDC2 expression correlated with a poorer prognosis, increased tumor malignancy, lymph node metastasis, larger tumor size, and advanced staging." (PMID 38790013, 2024). "We found that YTHDC2 inhibitor increased the number of tumor growth in the lungs of mice and the content of plasma exosome." (PMID 39303913, 2024). "The results of qPCR showed that METTL3 and IGF2BP3 were significantly overexpressed in the tumor cells, while YTHDC2 was significantly downregulated (p < 0.05)." (PMID 39717046, 2024). "YTHDC2 is a tumor suppressor gene that is typically expressed at high levels in normal tissues and at low levels in tumor tissues." (PMID 37711170, 2023). "Between them, YTHDC2 has been reported to promote mRNA degradation in both oncological and non-neoplastic diseases." (PMID 36810285, 2023). "Alterations in the expression of m6A writers (i.e. METTL3 and METTL14), erasers (i.e. FTO) or readers (i.e. YTHDC2 and YTHDF1), for example, are associated with tumor-suppressive or tumor-promoting scenarios." (PMID 36866275, 2023). "And YTHDC2 strengthens the translation of HIF-1α and TWIST1 by decoding the m6A modification at 5′UTR to promote EMT and cause tumor metastasis." (PMID 37437245, 2023). "Conversely, the results demonstrated a significant decrease in YTHDC2 expression in tumor tissues compared to normal tissues." (PMID 37474926, 2023). "Yang Li reported that YTHDC2 is a tumor suppressor gene in the head and neck, which is highly expressed in normal tissues but low in tumors." (PMID 35299954, 2022). "Through further analysis, the absolute expression of HNRNPC in tumor tissues was the highest, and the absolute expression of YTHDC2 was the lowest." (PMID 35581263, 2022). "Using cell-based experiments, mouse models, and clinical LUAD specimens (total 382), our data demonstrate the critical tumor suppressor roles of the m6A reader YTHDC2 in LUAD tumorigenesis." (PMID 33232910, 2021). "As for hsa-miR-96-5p/YTHDC2, high expression of YTHDC2 and hsa-miR-96-5p exhibited favorable and opposite outcome respectively, which was thus defined as a tumor-antagonizing pair." (PMID 33718187, 2021). "The results show that there is a considerable difference in YTHDC2 expression in the vast majority of malignant tumours, and moreover, YTHDC2 is tumour‐suppressive in most cancers and is oncogenic in a few tumours, respectively." (PMID 34312987, 2021). "In cohort #2 (n = 100), YTHDC2 was downregulated in the tumor compared to the adjacent tissues, and 62% (62/100) of acinar tissue were classified as YTHDC2low." (PMID 33232910, 2021). "The high expression of YTHDC2 is related to the malignancy of colon cancer and contributes to tumor metastasis." (PMID 33692959, 2021).